CCR8 (C-C motif chemokine receptor 8)
Diseases named in the same sentence as CCR8 in open-access papers (continued):
Sharing a sentence is not in itself a finding about the gene and the disease.
tumor (continued). "We observed that the OSCC secretome induced CCL18 gene expression in Teff and CCL18 was able to promote CCR8 expression, therefore it would be interesting to observe how the tumor environment is able to regulate this chemokine to promote CCR8+ cells." (PMID 34025655, 2021). "In this study, we examined the function of CCR8 in tumour immunosuppression using mice in which CCR8 expression has been genetically ablated." (PMID 33838058, 2021). "We next evaluated the expression pattern of the CCR8 protein within tumor single cell suspensions via multicolor flow cytometry." (PMID 33589525, 2021). "Collectively, our findings highlight the efficacy and safety of targeting CCR8 for the depletion of tumor-promoting ti-Tregs in combination with anti-PD-1 therapy." (PMID 33589525, 2021). "The expression of CCR8 was significantly increased in tumor tissues (P<0.001), while the expression of P2RY14 was significantly decreased (P<0.001)." (PMID 33692955, 2021). "We observed high levels of CCR8 expression on tumour‐infiltrating Treg cells which were abolished in Ccr8−/− mice." (PMID 33838058, 2021). "A significant increment was also observed in CCR8 expression within the Tregs and Teffs cultured with cancer secretome compared to control samples, suggesting the tumor environment was regulating CCR8 expression in both subsets." (PMID 34025655, 2021). "It has recently been proposed that disruption of CCR8 function using blocking anti‐CCR8 antibodies results in reduced accumulation of Treg cells within tumours and disruption of their immunosuppressive function." (PMID 33838058, 2021). "Subsequently, they showed that treatment with a CCR8-targeted depleting antibody specifically depleted intratumoral Tregs and promoted a robust anti-tumor immune response." (PMID 34868044, 2021). "Other tumor-specific Treg signature genes (e.g., CCR8, FCRL3, IL1R2) are exclusively expressed on tumor-infiltrating Tregs and absent in their peripheral counterparts." (PMID 33679808, 2021). "Defected DCs CCR8, a chemokine receptor mainly expressed on the Treg cells plays a crucial role in the CCR8+ Treg-mediated immunosuppression and is uniquely upregulated in human tumor-resident Treg." (PMID 34820403, 2021). "It has also been proposed, through experiments where anti‐CCR8 antibodies have been systemically administered, that blockade of CCR8 function impairs the ability of Treg cells to suppress anti‐tumour immunity." (PMID 33838058, 2021). "Consistently, we observed minimal impact of systemic CCR8 ablation on the frequency, phenotype and function of tumour‐infiltrating Treg cells." (PMID 33838058, 2021). "As shown in breast cancer research studies, these cells in the tumor niche express CCR8 (receptor for CCL1/I-309) and CCR4 (receptor for CCL17/thymus and activation regulated chemokine (TARC) and CCL22/macrophage derived chemokine (MDC))." (PMID 33114763, 2020). "In this model, activation of CCR8 on tumor cells is mediated by CCL1 expressed on SCS endothelial cells in LNs allowing tumor cell entry from the collecting lymphatic vessel into the SCS." (PMID 32111837, 2020). "This process is important in metastasis to lymph nodes in malignant melanoma, which often leads to increased CCR8 expression in the cancer cells of this tumor." (PMID 33076281, 2020). "BMS-986340 is a newly developed anti-CCR8 mAb which reduces sizeable CCR8+ Treg in a human tumor explant." (PMID 33519807, 2020). "High expression of CD4_C12-CTLA4 (tumor regulatory T cell, Tumor-Treg) markers, such as CCR8, RTKN2, and FOXP3, was observed in C1." (PMID 33584715, 2020). "We also noted that the tumor-infiltrating CD11b+CCR8+ cell subset responsible for the production of the greatest levels of the pro-inflammatory (IL-6, CCL3, CCL4) and pro-angiogenic (VEGF) factors among intra-tumoral myeloid cells." (PMID 31811337, 2020).
tumor (continued). "CCR8+ Tregs are a stable subtype of Tregs with enhanced immunosuppressive properties, and in tumor sites where CCR8+ Tregs are plentiful imply the inferior prognosis." (PMID 33519807, 2020). "The downregulated expression of IL-1, CTSW, NR1H3 and CCR8 (with HR < 1) indicated these molecules as tumor suppressors, whereas the upregulated expression levels of LY86, RABGEF1, CYFIP2 and SERINC3 (with HR > 1) indicated these molecules as oncogenes." (PMID 33816214, 2020). "CCL26 and CCR8 are related to the Ca2+ mobilization of cells, and CCR8 can also recruit Treg infiltration, thereby promoting tumor metastasis." (PMID 33330624, 2020). "CCR8+ Treg were reported as very potent suppressors, suggesting that this Treg subset is likely important in the creation of an immunosuppressive tumor microenvironment." (PMID 32014107, 2020). "Recent independent studies have demonstrated that CCR8 was a specific marker selectively upregulated by tumor-infiltrated Tregs in CRC." (PMID 33419310, 2020). "Another chemokine receptor, CCR8, was described to facilitate LN metastasis of lymph-derived tumor cells." (PMID 32111837, 2020). "CC-type chemokine ligand 1 (CCL1) is expressed on the surface of LECs which bind CC-type chemokine receptor 8 (CCR8) on the surface of tumor cells and thus help in their trans-endothelial migration." (PMID 31921870, 2019). "CCR8 is a member of chemokine receptor family and plays a pivotal role in recruitment of regulatory T (Treg) cells to tumor by the CCL1-CCR8 axis." (PMID 32047513, 2019). "It is also possible that depletion of CCR4-expressing T cells leaves other tumor-infiltrating Tregs unaffected, such as the CCR8-expressing Tregs that have been noted in multiple tumor types." (PMID 31801624, 2019). "CCR8 also supports cancer dissemination, as its ligand CCL1, produced by lymphatic endothelial cells in the subcapsular sinus, can attract CCR8+ tumor cells to the lymph nodes to promote metastasis." (PMID 30591657, 2018). "The chemokine receptor CCR8 resulted overexpressed in tumor Tregs and represents a novel target in immunotherapeutic approaches for BC treatment." (PMID 29879107, 2018). "CCR8 induction was obtained by co-culturing activated peripheral blood Treg cells with tumor explants, indicating the crucial role of tumor microenvironment." (PMID 29879107, 2018). "Enrichment of LAYN, MAGEH1, and CCR8 in whole tumor samples correlated significantly with reduced 5-year survival rate of CRC and NSCLC patients." (PMID 29887862, 2018). "The circulating monocytic CD33highCD11b+ and granulocytic CD33lowCD11b+ myeloid cell subset as well as CD11b+ tumor infiltrating TAMs showed increased expression of the CCL1 chemokine receptor CCR8." (PMID 28197019, 2017). "The tumor infiltrating CD11b+CCR8+ myeloid subset produced significant amount of proinflammatory IL-6 and angiogenic VEGF and induced the differentiation of CD4+FoxP3+ regulatory T-cells." (PMID 28197019, 2017). "CCL1 is another chemokine produced by the SCS LEC, which has been shown to control CCR8+ tumor cell entry and subsequent migration and colonization in the LN cortex." (PMID 28220121, 2017). "Inhibition of CCR8 additionally prevented tumor cells from lymph node entry, creating an arrest of tumor cells in the afferent lymphatic vessels." (PMID 28590032, 2017). "CCR8 inhibition results in tumor cell arrest in collecting lymphatics at the junction with the LN subcapsular sinus." (PMID 28036019, 2016). "Chemokine (C-C motif) receptor (CCR8) is one of the novel candidates of tumor prediction because there have been various literatures reported the special behaviors of CCR8 in different pathogenesis." (PMID 26716905, 2016). "We observed that tumor-infiltrating FoxP3+ T cells highly expressed CCR8, while lymph node-residing FoxP3+ T cells express CCR8 at a relatively lower level." (PMID 22292042, 2012).
tumor (continued). "Allowing the radiolabeled antibody to reach its highest uptake in the tumor before giving immunotherapy will allow for more profound killing of CCR8+ Tregs in the tumor before CD8+ T cells and other immune cells will start coming into the tumor microenvironment." (PMID 41302499, 2025). "In addition, ablation of tumor-infiltrating Tregs expressing CCR8, one of the primary receptors for CCL8, can elicit antitumor immunity and improve the efficacy of anti–PD-1 therapy." (PMID 39774471, 2025). "In our previous report, CCR8+ Tregs made up ~ 40% of the total Treg population within the tumor." (PMID 40274705, 2025). "Notably, treatment with the lactate production inhibitor oxamate reduces tumor-infiltrating Treg cells by suppressing CCR8 expression, thereby enhancing CAR-T cell activation within the tumor microenvironment." (PMID 41152975, 2025). "More CCR8+ Tregs were observed to accumulate at the tumor invasion front." (PMID 41323783, 2025). "Indeed, the top 30 significantly enriched immune modulators in ME patients included CCL8, a ligand for the tumour infiltrating Treg cells chemokine receptor CCR8, PVR, a ligand for the T cell checkpoint protein TIGIT and ITGA8, which is known to activate TGFb." (PMID 39915477, 2025). "Finally, in vivo presence of CCR8+ ti-Tregs was established by administering 111In-labeled anti-CCR8 and control mAbs to tumor bearing mice and imaging them with microSPECT/CT." (PMID 41035646, 2025). "Notably, the anti-tumor efficacy of combining PARPi with the anti-CCR8 mAb is significantly superior to that of either agent alone." (PMID 40830526, 2025). "From a mechanistic point of view, metformin can reduce histone acetylation at the CCR8 promoter and inhibit CCR8 expression on tumor-infiltrating Treg cells by upregulating AMPK-activated Sirtuin 2 (SIRT2), thus enhancing the effectiveness of anti-PD-1 immunotherapy." (PMID 39944825, 2025). "Experiments in mice suggested that the blockade of the homing receptor (CXCR4) and chemokine receptor (CCR4/CCR8) may inhibit Treg infiltration and tumor homing." (PMID 40427000, 2025). "Additionally, lactylation of CCR8 in Tregs enhances their immunosuppressive function, further dampening anti-tumor immunity." (PMID 40223940, 2025). "Finally, a population of highly suppressive, activated CCR8+ Tregs, similar to those found in the decidua, accumulate at tumor sites and contribute to the creation of an immune-privileged environment that enables cancer immune evasion." (PMID 41368133, 2025). "The chemokine receptor CCR8 is selectively expressed on tumor-infiltrating Tregs." (PMID 40308582, 2025). "Anti-TNFR2 mAb treatment might destroy the chemotactic attraction between CCL18+ macrophages and CCR8+ Tregs, leading to a reduction in tumour-infiltrating CCR8+ Tregs." (PMID 37935468, 2024). "Consequently, these findings raise doubts on the promise of CCR8 antagonists as potential anti-tumor agents." (PMID 38231448, 2024). "Our data suggest that local CCR8+ Treg accumulation is associated with reduced CD8+ T cell cytotoxic activity and poor prognosis in LSCC patients, highlighting the biological role and clinical significance of CCR8+ Tregs in the tumor microenvironment." (PMID 38783281, 2024). "It has been shown that CCR8 is dispensable for Treg accumulation at tumor sites." (PMID 38231448, 2024). "However, a recent study highlighted the inhibitory effect of IPG7236, a selective small molecule CCR8 antagonist, on tumor growth." (PMID 38231448, 2024). "The aim of our study was to generate a cellular model for TITRs that could be used to study the role of CCR8 signaling and would allow to evaluate the potential of small molecule CCR8 antagonists in future anti-tumor application." (PMID 38231448, 2024). "Targeting intratumoral CCR8-positive Treg cells with an anti-CCR8 mAb could potentially induce tumor regression and promote lasting antitumor memory." (PMID 38500876, 2024).
tumor (continued). "Monoclonal antibody-based CCR8 targeted treatment shows significant inhibition in tumor growth." (PMID 38721308, 2024). "CCL1 binding to CCR8 on tumor cells drives their proliferation, migration, and metastasis." (PMID 39796695, 2024). "Furthermore, it appears that the expression of CCR8 is highly restricted to tumor-infiltrating Treg cells." (PMID 38318526, 2024). "Tumor-infiltrated Tregs with higher expression of CCR8 produced more IL10 molecules in vitro." (PMID 38169378, 2024). "CCR8 is highly expressed in tumors and tumor infiltrating Treg cells." (PMID 39136031, 2024). "Disrupting CCR8 signaling could potentially inhibit tumor growth by attenuating the suppression of cytotoxic lymphocytes." (PMID 38720887, 2024). "Histological evaluation using the region of interest (ROI) protocol showed that GzmB expression levels in CD8+ T cells were decreased in areas with high infiltration of CCR8+ Tregs, suggesting a suppressive effect of CCR8+ Tregs on T cell cytotoxicity in the local tumor microenvironment." (PMID 38783281, 2024). "Additionally, TAMs overexpress CCL1, the ligand of CCR8 expressed on Tregs, to attract Tregs into the tumor area, inhibiting T cell immunity and promoting tumor growth." (PMID 38957393, 2024). "Additionally, CCR8 is highly expressed by tumor-infiltrating Tregs that contribute to immune evasion, while the expression on peripheral blood Treg is lower." (PMID 36765704, 2023). "To further test the utility of assessment of early TME responses to Treg cell depletion for identifying combinatory therapeutic modalities, we subjected KP tumor transplanted mice to a similar short-term treatment with CCR8 antibody and a selective CCR2 antagonist RS-504393 (CCR2i)." (PMID 37127830, 2023). "MAb1 detects the native conformation of human CCR8, as verified by its ability to bind to a subset of Treg cells present within human peripheral blood mononuclear cells (PBMCs) or dissociated tumor cells (DTCs) to a similar extent as a commercially available antibody." (PMID 38040762, 2023). "Notably, CCR8+Tregs from healthy tissues presented multiple similarities with CCR8+ Tregs isolated from tumor sites, thus strongly implicating the contribution of these cells to the human tissue repair program in both health and disease." (PMID 38136421, 2023). "However, the specific mechanisms underlying changes in phenotypes and immunosuppressive functions of CD4+CCR8+ Tregs recruited into tumor tissues are still unclear and need to be further studied." (PMID 37950246, 2023). "Moreover, Haruna found that the CCR8+ cell depletion from tumor-infiltrating cell (TIC) culture enhances the function of CD8 T cells." (PMID 36776832, 2023). "CCR8+ tumor-resident Tregs could be used as a reasonable target for cancer immunotherapy, and provide a new idea for selectively targeting intratumoral dysfunction or cell depletion of Tregs." (PMID 37950246, 2023). "Additionally, the engagement of CCL1 with CCR8 expressed on tumor cells (e.g., melanoma, bladder cancer) promoted tumor cell proliferation, migration, and metastasis." (PMID 37108657, 2023). "In this study, the impact of the tumor immune microenvironment (TIME) on specific gene expression (LAYN, MAGEH1, and CCR8) in tumor-infiltrating Tregs cells was confirmed, and these gene expressions were found to be correlated with immune therapy response, tumor-suppressive activity, and prognosis." (PMID 38077354, 2023). "Resting (CCR8-negative) tumor-associated Treg cells are probably not actively engaged in suppressing anti-tumor immunity and would not be affected by this treatment." (PMID 35158783, 2022). "Moreover, ACP5, MAGEH1, TNFRSF9 and CCR8 were especially populated in tumor-infiltrating Tregs and IKZF2 was only highly expressed in paratumor-infiltrating Tregs." (PMID 35562760, 2022). "The discussion includes an assessment of how the removal of CCR8-expressing cells might affect both anti-tumor immunity as well as immune homeostasis at remote sites." (PMID 35158783, 2022).
tumor (continued). "Recently, Campbell and coworkers proposed a CCR8-dependent depletion of tumor infiltrating Tregs based on the highly restricted expression of this receptor on tumor infiltrating Tregs as compared to both their circulating counterpart and to intratumoral effector T cells in different human tumors." (PMID 35874810, 2022). "Tumor growth was inhibited by anti-CCR8 antibody administration (n = 10)." (PMID 35354899, 2022). "Furthermore, this strategy exploits activated T cell derived CCL1 to potentialize a positive feedback loop in CCR8+ cells recruitment to the tumor site." (PMID 35211124, 2022). "One may speculate that interference with CCR8+ tumor Treg cells could not only reduce suppression of anti-tumor immunity but also impair tumor repair mechanisms, which is another potentially beneficial effect of CCR8-targeted immunotherapy." (PMID 35158783, 2022). "In addition, anti-CCR8 CAR T cells significantly suppressed MT-4 tumor progression in vivo and prolonged the survival of MT-4 tumor-bearing mice." (PMID 35693763, 2022). "Recent studies reported selective CCR8 expression on tumor-infiltrating Tregs17–23." (PMID 35354899, 2022). "Co-expression of CCR8 may also suggest overlapping functionalities in skin and tumor Treg cells that may go well beyond local immunosuppression." (PMID 35158783, 2022). "Elevated CCR8 discriminates highly suppressive tumor Tregs from systemic lymphoid tissue Tregs." (PMID 35565306, 2022). "The mAb therapy targeting CCR8+ Tregs could obviously inhibit tumor growth and improve the prognosis in CRCs by increasing tumor‐specific T cells." (PMID 35474948, 2022). "The physiological significance of CCR8 on tumor Treg cells is not clear at present but, based on tumor models in mice, appears unlikely to be associated with the recruitment of tumor Tregs cells." (PMID 35158783, 2022). "In addition, CCR8 was largely expressed on tumor infiltrating Treg cells, indicating that anti-CCR8 CAR T cells did not impair their anticancer immune response." (PMID 35693763, 2022). "We recently reported that mice that showed tumor regression with anti-CCR8 therapy rejected re-inoculated tumors because of the formation of memory T cells, whereas mice in which tumors were surgically removed failed to form memory T cells and thus showed tumor regrowth." (PMID 35354899, 2022). "Whereas a substantial proportion of Foxp3+ Treg cells within tumours of WT animals were positive for anti‐CCR8 antibody staining, this signal was abolished upon cells infiltrating tumours of Ccr8−/− animals, confirming both the target and specificity of the antibody used." (PMID 33838058, 2021). "Notably, all six expression-based markers for human TI-Tregs, TIGIT, TNFRSF9, ICOS, CCR8, CD83, and CCRL2, were ranked within the top 10%, which indicates that they are likely to play major roles in tumor-associated Treg functions." (PMID 33598101, 2021). "This anti-tumor activity is closely associated with the increase of tumor-specific T cells, the enhancement of CD4 + T cells and CD8 + T cell infiltration and the significant decrease of tumor resident CD4 + CCR8 + Treg." (PMID 34884642, 2021). "LLC-OVA tumor-bearing mice were treated with Nb-Fc1A, which blocks CCR8 but cannot perform any Fc-mediated function (termed Anti-CCR8 (block) in the Figures), and with Nb-Fc1B, which also blocks CCR8 but mediates ADCC (termed Anti-CCR8 (ADCC))." (PMID 33589525, 2021). "Pearson correlation coefficients were calculated, and the results indicated that BGN presented the strongest correlations with TIIC markers for monocytes (CD86, CD115), tumor-associated macrophages (TAMs) (IL-10, CCL2, CD68), M2 macrophages (CD163, VSIG4, and MS4A4A) and Tregs (FOXP3, CCR8, TGFβ)." (PMID 35096572, 2021). "Furthermore, the infiltration of CCR8-expressing Treg cells in the tumor microenvironment correlates with poor clinical outcomes in breast cancer." (PMID 34885241, 2021).